FTMT (ferritin mitochondrial)
Description:
Catalyzes the oxidation of ferrous iron(II) to ferric iron(III) and stores iron in a soluble, non-toxic, readily available form. Important for iron homeostasis. Iron is taken up in the ferrous form and deposited as ferric hydroxides after oxidation.
Synonyms: MtF
Tractability: No criterion of Open Targets' tractability assessment is met for any kind of drug.
Gene: Protein-coding gene on chromosome 5 (121,851,882 to 121,852,833, forward strand). Ensembl gene ENSG00000181867.
Subcellular location: Mitochondrion
Pathways (Reactome):
Transport of small molecules: Iron uptake and transport
Gene Ontology:
Molecular function: ferroxidase activity; iron ion binding; ferric iron binding; ferrous iron binding
Biological process: intracellular iron ion homeostasis; protein maturation; iron ion transport
Cellular component: mitochondrion; nucleus; mitochondrial matrix
Genetic constraint (gnomAD): Loss-of-function variants: 8 observed, 12.48 expected, observed/expected ratio (o/e) 0.64, 90% interval 0.38 to 1.16. The upper end of that interval is the gene's LOEUF score, 1.16, which puts it in group 5 of 6, group 1 being the genes least tolerant of losing a copy. Missense variants: 393 observed, 321.93 expected, observed/expected ratio (o/e) 1.22, 90% interval 1.12 to 1.33. Synonymous variants: 174 observed, 140.02 expected, observed/expected ratio (o/e) 1.24, 90% interval 1.1 to 1.41.
Homologues: Orthologues: chimpanzee FTMT (98% identical), macaque FTMT (93% identical), pig FTMT (80% identical), mouse Ftmt (76% identical), rat Ftmt (75% identical), guinea pig FTMT (67% identical), rabbit FTMT (67% identical), Caenorhabditis elegans ftn-2 (39% identical), zebrafish zgc:56095 (36% identical), Caenorhabditis elegans ftn-1 (35% identical), Drosophila melanogaster Fer3HCH (33% identical), zebrafish zgc:172145 (21% identical). Paralogues in human: FTH1 (60% identical), FTHL17 (48% identical), FTL (39% identical).
Diseases named in the same sentence as FTMT in open-access papers:
FTMT is named in the same sentence as 40 diseases in open-access papers, as found by Europe PMC text mining. Sharing a sentence is not in itself a finding about the gene and the disease. The quoted sentences say what the papers report.
neuroblastoma (13 papers, 2015 to 2025). Neuroblastoma (NB) is the most common solid, extracranial childhood tumor. "Our previous studies showed that reactive oxygen species (ROS) and inflammatory cytokines, such as TNF-α, IL-1β, and IL-6, induced FtMt expression in the human neuroblastoma cell line IMR-32." (PMID 35008961, 2022). "Research suggests that overexpression of Mitochondrial ferritin (FtMt) in dopaminergic neuroblastoma cell line SH-SY5Y cells can significantly inhibit erastin-induced ferroptosis." (PMID 35530363, 2022). "We also demonstrated that FTMT expression was increased in response to TNF-α via NF-κB activation in the human neuroblastoma cell line IMR-32." (PMID 32455741, 2020). "To address this issue, we transfected SH-SY5Y neuroblastoma cells with a FtMt expression plasmid and isolated cell lines with stable expression of FtMt at high, medium and low levels." (PMID 30670947, 2018). "Overexpression of FtMt significantly slowed the replication of FtMt transfected SH-SY5Y neuroblastoma cells, both in culture and after in vivo transplantation of overexpressing cells to immune-deficient mice." (PMID 30670947, 2018). "An FtMt overexpressing neuroblastoma SH-SY5Y cell line is used to better investigate the functions of FtMt." (PMID 28840060, 2017). "Here, we overexpressed FtMt in neuroblastoma SH-SY5Y cells and induced oxidative stress by treating with extracellular H2O2." (PMID 28840060, 2017). "We used an FtMt-overexpressed neuroblastoma SH-SY5Y cell line and induced ferroptosis by erastin treatment." (PMID 28066232, 2016). "We found that overexpression of FtMt in neuroblastoma SH-SY5Y cells significantly inhibited erastin-induced ferroptosis, which very likely was achieved by regulation of iron homeostasis." (PMID 28066232, 2016). "In addition, a study showed that mitochondrial ferritin (FTMT) inhibits erastin-induced ferroptosis in neuroblastoma cells, suggesting that iron storage proteins play an important role in inhibiting ferroptosis." (PMID 37408372, 2023). "Furthermore, high levels of FTMT was detected in cardiomyocytes of Friedreich Ataxia patients, while downregulation of FTMT was found in Neuroblastoma and Neurospongioma." (PMID 33260500, 2020). "Thus, we overexpressed FtMt gene in the neuroblastoma SH-SY5Y cells to see if an increase of FtMt expression can sequester more free iron and counter the H2O2-induced iron accumulation and cell damage." (PMID 28840060, 2017). "A more recent study showed a downregulation of FTMT in Neuroblastoma and in Neurospongioma, where it has been proposed that FTMT could be used as a target to inhibit neuronal cell proliferation through its overexpression." (PMID 27625068, 2016). "Conversely, FtMt overexpression greatly suppresses SH-SY5Y neuroblastoma cells’ proliferation." (PMID 25213357, 2015). "For instance, we observed increased FtMt expression in human neuroblastoma cells (IMR-32) treated with proinflammatory cytokines, while other researchers found increased FtMt expression in SH-SY5Y treated with hydrogen peroxide." (PMID 35008961, 2022). "Our data showed that TNF-α-upregulated FTMT expression was inhibited by an NF-κB inhibitor, BAY 11-7082, similar to our previous study using IMR-32 neuroblastoma cells." (PMID 32455741, 2020). "Moreover, the overexpression of mitochondrial ferritin (FTMT), a mitochondria iron-storage protein, inhibits ferroptosis in neuroblastoma cells, indicating an essential antiferroptotic role in mitochondria." (PMID 39975561, 2025). "Moreover, the overexpression of ferritin mitochondrial (FTMT), an iron-storage protein in mitochondria, inhibits erastin-induced ferroptosis in neuroblastoma cells, indicating a wide anti-ferroptotic role for iron-storage proteins." (PMID 33268902, 2021).
neuroblastoma (continued). "Our results indicated that overexpression of FtMt significantly protected neuroblastoma cells from H2O2 induced apoptosis, which was due to the restriction effects of FtMt on the increase of intracellular ROS and the decrease of MMP, thus protecting cells from oxidative stress-mediated apoptosis." (PMID 28840060, 2017). "Our previous studies have found that FtMt overexpression in neuroblastoma SH-SY5Y cell increased its resistance to oxidative stress, indicating FtMt is not only involved in storing cellular iron, but may also play a role in protecting mitochondria from iron-dependent oxidative damage." (PMID 28066232, 2016). "Additionally, we found that the expression of FtMt in human normal brain tissue was significantly higher than that of neuroblastoma, but not higher than that of neurospongioma." (PMID 25213357, 2015).
Alzheimer disease (9 papers, 2011 to 2022). A progressive, neurodegenerative disease characterized by loss of function and death of nerve cells in several areas of the brain leading to loss of cognitive function such as memory and language. "It was also found that, in the pathological conditions associated with mitochondrial iron overload, such as Alzheimer’s disease, PD, and sideroblastic anemia, the FtMt expression was largely induced." (PMID 24596558, 2014). "Our previous studies demonstrated that FtMt prevents neuronal cells from oxidative stress injury in iron-related neurological diseases, including Alzheimer’s disease and Parkinson’s disease." (PMID 35883748, 2022). "Our previous studies have indicated the neuroprotective role of FtMt in Parkinson’s disease and Alzheimer’s disease." (PMID 28840060, 2017). "Studies from our laboratory showed that in Alzheimer’s disease, FtMt overexpression attenuated the β-amyloid induced neurotoxicity, which on the other hand increased significantly when FtMt expression was knocked down." (PMID 24596558, 2014). "In some neurodegenerative diseases characterized by iron overload, including Alzheimer’s disease and Parkinson’s disease (PD), increased expression of FtMt was observed." (PMID 24596558, 2014). "FtMt is involved in pathogenesis of neurodegenerative diseases, as its increased expression has been observed in Alzheimer’s disease, restless legs syndrome and Friedreich’s ataxia." (PMID 24596558, 2014). "In addition, the increased expression of FtMt in Alzheimer’s diseases can be a way to diagnose the disease early and to predict its progress." (PMID 34440737, 2021). "In brains that experience the symptoms of Alzheimer’s Disease, the FTMT overexpression induced by pro-inflammatory cytokines led to decreased amyloid-β production while for the Restless Legs Syndrome, the increased FTMT expression contributes to the cytosolic iron deprivation." (PMID 33260500, 2020). "We and others have indicated that FtMt-deficient mice do not show any evident phenotypes or iron-related disorders under baseline feeding conditions but that FtMt exerts significant protective effects under pathological conditions, such as in Alzheimer’s disease and Parkinson’s disease." (PMID 33953171, 2021).
Friedreich ataxia (6 papers, 2014 to 2025). An inherited condition that affects the nervous system and causes movement problems. "After FtMt overexpression in fibroblasts of patients with Friedreich’s Ataxia, ROS production decreased and Fe-S mitochondrial enzyme activity partially recovered." (PMID 39396974, 2024). "In Friedreich ataxia, the cells are under chronic oxidative stress and, in this case, an increase in FtMt expression would be beneficial for the cell." (PMID 34440737, 2021). "FtMt has attracted increasing attention, as its misregulation has been observed in several neurological disorders, such as Alzheimer and Parkinson diseases, restless legs syndrome, Friedreich ataxia and age-related macular degeneration." (PMID 41372147, 2025). "These treatments up-regulate FtMt expression even in fibroblasts derived from a Friedreich ataxia patient, where it might exert a beneficial effect against mitochondrial oxidative damage." (PMID 27625068, 2016). "Furthermore, the increased expression of FTMT was detected in cardiomyocytes of Friedreich Ataxia (FRDA) patients." (PMID 27625068, 2016).
Parkinson disease (6 papers, 2014 to 2025). A progressive degenerative disorder of the central nervous system characterized by loss of dopamine producing neurons in the substantia nigra and the presence of Lewy bodies in the substantia nigra and locus coeruleus. "Mitochondrial ferritin (FtMt) protects against oxidative stress and is found at higher levels in diseases associated with abnormal iron accumulation, including Alzheimer’s and Parkinson’s." (PMID 40393986, 2025). "As a key mitochondrial iron storage protein, the protective role of FtMt in neurodegenerative diseases has also been reported in AD and Parkinson’s disease models." (PMID 36364859, 2022). "Our previous studies have found that FtMt overexpression protected 6-hydroxydopamine-induced dopaminergic cell damage, potentially playing an important neuroprotective role in Parkinson’s Disease." (PMID 28840060, 2017). "It is also found that, by maintaining mitochondrial iron homeostasis, FtMt could prevent 6-hydroxydopamine induced dopaminergic cell damage in Parkinson’s disease." (PMID 24596558, 2014).
iron deficiency (4 papers, 2015 to 2023). "Mutations in FTMT result in mitochondrial iron overload and cytoplasmic iron deficiency, demonstrating that FTMT functions actively in iron transport to the cytoplasm in addition to mitochondrial iron storage." (PMID 37629039, 2023). "Iron deficiency in the cytosol, from iron relocation to the mitochondria by the FtMt, reduces the production and maturation of iron-dependent proteins." (PMID 34440737, 2021). "On the contrary, overproduction of FTMT can cause cytosolic iron deficiency with low ferritin and high TfR1 levels." (PMID 30577543, 2018). "All these results indicated that in RLS there is an alteration of cellular iron homeostasis, and a possible explanation for this iron deficiency in neurons could be the higher expression of FtMt." (PMID 34440737, 2021).
ischemic stroke (3 papers, 2021 to 2022). A stroke disorder caused by obstruction of blood flow to the brain, due to thrombotic (local blood clot formation) or embolic (due to a blood clot or other material traveling from another site) event. "In order to determine the effects of FtMt on endothelial cell apoptosis after ischemic stroke, we assessed the expression of biomarkers for apoptosis in BMVECs of the WT and OE mice after I/R." (PMID 35883748, 2022). "In summary, our data identify a previously unexplored effect for FtMt in the BBB and provide evidence that iron-mediated oxidative stress in BMVECs is an early cause of BMVECs damage and BBB breakdown in ischemic stroke." (PMID 35883748, 2022). "From the results, it is clear that FtMt plays a very important role in protecting against brain damage due to ischemic stroke." (PMID 34440737, 2021). "In this study, we demonstrate that FtMt deficiency can induce iron overload, which exacerbates L-ROS production and ferroptosis in I/R; conversely, overexpression of FtMt affords protection to neuronal cells after ischaemic stroke." (PMID 33953171, 2021). "Our data provide a new perspective for exploring the protective role of FtMt in ischemic stroke." (PMID 35883748, 2022). "We observed that FtMt was indeed expressed in BMVECs and the level of FtMt was significantly upregulated in ipsilateral (Ips) BMVECs compared with the contralateral (Con) samples during ischemic stroke." (PMID 35883748, 2022). "In brief, our results provide evidence that FtMt plays a critical role in protecting against cerebral I/R-induced ferroptosis and subsequent brain damage, thus providing a new potential target for the treatment/prevention of ischaemic stroke." (PMID 33953171, 2021). "To verify whether FtMt overexpression increases the BBB integrity by attenuating the degradation of junction-related proteins that occurs after ischemic stroke, we immunofluorescence-stained the tight junctional molecules claudin-5, occludin and ZO-1, along with the endothelial marker CD31." (PMID 35883748, 2022). "Finally, our data suggest that FtMt may be a potential therapeutic target in ischaemic stroke." (PMID 33953171, 2021). "The understanding of the role of FtMt in maintaining BBB integrity and function may represent a target for the development of safe and effective therapeutic approaches to protect the BBB integrity in ischemic stroke." (PMID 35883748, 2022). "Thus, excessive free iron, oxidative stress and inflammation form a vicious feedback cycle in ischaemic stroke, and the absence of FtMt exacerbates this cycle." (PMID 33953171, 2021).
osteoporosis (3 papers, 2024 to 2026). A condition of reduced bone mass, with decreased cortical thickness and a decrease in the number and size of the trabeculae of cancellous bone (but normal chemical composition), resulting in increased fracture incidence. "Therefore, we identify a novel pathway in which FTMT-mediated disruption of mitophagy drives iron-induced osteoporosis." (PMID 41990575, 2026).
ovarian carcinoma (3 papers, 2017 to 2025). A malignant neoplasm originating from the surface ovarian epithelium. "We found that Roflumilast could phosphorylate CREB to up-regulate the level of FtMt, and the promoter region of FtMt was reported to harbor the binding site of CREB, which implicated that the increased expression of FtMt in ovarian cancer was attributed to the transcription of CREB." (PMID 29348829, 2017). "In this study, CREB was demonstrated to directly promote the transcription of FtMt, and the increased expression of FtMt inhibited the proliferation and induced G0/G1 arrest of ovarian cancer cells." (PMID 29348829, 2017). "The potential mechanisms were analyzed and found that roflumilast activated cAMP/PKA/CERB signals to up-regulate FtMt expression for inhibiting the development of ovarian cancer." (PMID 29348829, 2017). "Here, we uncovered the anti-tumor effects of PDE4 inhibitor Roflumilast for ovarian cancer via activating PKA/CREB/FtMt pathway." (PMID 29348829, 2017). "We then analyzed the relationship between cAMP/PKA/CREB and the up-regulation of FtMt in ovarian cancer." (PMID 29348829, 2017). "In addition, we found that Roflumilast-induced phosphorylated CREB directly promoted transcription of FtMt, indicating that Roflumilast up-regulated the expression of FtMt in ovarian cancer via cAMP/PKA/CREB signals." (PMID 29348829, 2017). "The anti-tumor role of Roflumilast in vivo was also demonstrated, the treatment of roflumilast effectively inhibited tumor proliferation and elevated the FtMt expression to restrict the tumor growth via the activation of cAMP/PKA/CREB signals in ovarian cancer." (PMID 29348829, 2017). "Interestingly, the hallmarks of tumor contain dysregulation of metabolic activity and oxygen consumption, but the role of FtMt in cancer is totally unknown in ovarian cancer." (PMID 29348829, 2017). "Interestingly, forced expression of FtMt in ovarian cancer enhanced the apoptosis and inhibited tumor growth and the PKA inhibitor H89 and knockdown of CREB significantly repressed the expression of FtMt to restore the tumor proliferation and inhibit apoptosis." (PMID 29348829, 2017). "Regarding ovarian cancer cells, roflumilast induces apoptosis and prevents tumor progression by activating the cAMP/PKA/CREB pathway and upregulating mitochondrial ferritin (FtMt) levels in the two types of cells (OVCAR3 and SKOV3)." (PMID 35832555, 2022).
sideroblastic anemia (3 papers, 2013 to 2021). "An example is the presence of FtMt in erythroblasts, which is a hallmark of sideroblastic anemia." (PMID 34440737, 2021). "FtMt expression is also high in normal spermatozoa and in sideroblasts from patients with sideroblastic anemia." (PMID 34440737, 2021). "In humans, FTMT is primarily expressed in the testes, and in sideroblasts of patients with sideroblastic anemia, but immunohistochemical experiments have identified FTMT in the heart, spinal cord, kidney, pancreas, and smooth muscle." (PMID 34571846, 2021). "In addition, in some patients with sideroblastic anemia, FtMt was also found in erythrocytes (called siderocytes)." (PMID 34440737, 2021). "Finally, FTMT was not expressed in normal erythroblasts but was highly expressed in patients with sideroblastic anemia." (PMID 24341334, 2013).
age-related macular degeneration (2 papers, 2021 to 2025). Age-related loss of vision in the central portion of the retina (macula), secondary to retinal degeneration. "A mutation in the FtMt coding gene was then identified in patients affected by age-related macular degeneration (AMD), a multifactorial disease affecting the central retina (macula)." (PMID 34440737, 2021).
Cerebral ischemia (2 papers, 2021 to 2024). Restriction of arterial blood supply to the brain associated with insufficient oxygenation to support the metabolic requirements of the tissue. "FTMT has a critical role in iron homeostasis by attenuating cerebral ischemia/reperfusion injuries that result from ferroptosis inhibition." (PMID 38755566, 2024).
glioma (2 papers, 2023). A benign or malignant brain and spinal cord tumor that arises from glial cells (astrocytes, oligodendrocytes, ependymal cells). "The authors reported that FTMT was highly expressed in glioma tissues in adults, suggesting its possible role in the progression of glioma in adults and pediatrics." (PMID 37444408, 2023). "Due to the lack of the “FTMT” gene in the CGGA database, we analyzed the expression of 18 ferroptosis suppressor genes in gliomas." (PMID 37510310, 2023).
memory impairment (2 papers, 2017 to 2020). "Notably, the mitochondrial iron storage protein FtMt could prevent mitochondria from iron-induced oxidative injury, and FtMt knockout significantly aggravated the learning and memory impairment in an AD mouse model." (PMID 33204324, 2020).